YME1L1 (YME1 like 1 ATPase)
Description:
ATP-dependent metalloprotease that catalyzes the degradation of folded and unfolded proteins with a suitable degron sequence in the mitochondrial intermembrane region. Plays an important role in regulating mitochondrial morphology and function by cleaving OPA1 at position S2, giving rise to a form of OPA1 that promotes maintenance of normal mitochondrial structure and mitochondrial protein metabolism. Ensures cell proliferation, maintains normal cristae morphology and complex I respiration activity, promotes antiapoptotic activity and protects mitochondria from the accumulation of oxidatively damaged membrane proteins. Required to control the accumulation of nonassembled respiratory chain subunits (NDUFB6, OX4 and ND1). Involved in the mitochondrial adaptation in response to various signals, such as stress or developmental cues, by mediating degradation of mitochondrial proteins to rewire the mitochondrial proteome. Catalyzes degradation of mitochondrial proteins, such as translocases, lipid transfer proteins and metabolic enzymes in response to nutrient starvation in order to limit mitochondrial biogenesis: mechanistically, YME1L1 is activated by decreased phosphatidylethanolamine levels caused by LPIN1 activity in response to mTORC1 inhibition. Acts as a regulator of adult neural stem cell self-renewal by promoting mitochondrial proteome rewiring, preserving neural stem and progenitor cells self-renewal (By similarity). Required for normal, constitutive degradation of PRELID1. Catalyzes the degradation of OMA1 in response to membrane depolarization. Mediates degradation of TIMM17A downstream of the integrated stress response (ISR). Catalyzes degradation of MICU1 when MICU1 is not assembled via an interchain disulfide. Cleaves STARD7 mitochondrial targeting sequence.
Synonyms: PAMP; YME1L; FTSH; MEG4; OPA11
Tractability: Antibody: UniProt predicts a signal peptide or a membrane-spanning region. PROTAC: ubiquitination databases record sites on it; its protein half-life has been measured.
Gene: Protein-coding gene on chromosome 10 (27,110,088 to 27,155,266, reverse strand). Ensembl gene ENSG00000136758.
Subcellular location: Mitochondrion inner membrane; Mitochondrion
Subcellular location (Human Protein Atlas): Mitochondria; Nuclear bodies
Pathways (Reactome):
Cellular responses to stimuli: Cellular response to mitochondrial stress
Metabolism of proteins: Mitochondrial protein degradation
Transport of small molecules: Processing of SMDT1
Gene Ontology:
Molecular function: ATP hydrolysis activity; ATP-dependent peptidase activity; protein binding; metalloendopeptidase activity; ATP binding
Biological process: cell population proliferation; cellular response to starvation; mitochondrial protein catabolic process; mitochondrial protein processing; mitochondrion organization; negative regulation of apoptotic process; positive regulation of mitochondrial fusion; protein hexamerization; protein quality control for misfolded or incompletely synthesized proteins; mitochondrial inner membrane fusion; neuronal stem cell population maintenance; regulation of stem cell division; proteolysis
Cellular component: membrane; mitochondrial inner membrane; mitochondrion
Genetic constraint (gnomAD): Loss-of-function variants: 27 observed, 64.02 expected, observed/expected ratio (o/e) 0.42, 90% interval 0.31 to 0.58. The upper end of that interval is the gene's LOEUF score, 0.58, which puts it in group 2 of 6, group 1 being the genes least tolerant of losing a copy. Missense variants: 529 observed, 773.52 expected, observed/expected ratio (o/e) 0.68, 90% interval 0.64 to 0.74. Synonymous variants: 247 observed, 263.86 expected, observed/expected ratio (o/e) 0.94, 90% interval 0.84 to 1.04.
Gene-disease validity (ClinGen):
ClinGen rates the evidence that YME1L1 causes each of these diseases.
mitochondrial disease (autosomal recessive): Limited.
optic atrophy 11 (autosomal recessive): Limited.
Homologues: Orthologues: chimpanzee YME1L1 (100% identical), macaque YME1L1 (99% identical), rabbit YME1L1 (97% identical), dog YME1L1 (96% identical), mouse Yme1l1 (95% identical), rat Yme1l1 (95% identical), tropical clawed frog yme1l1 (84% identical), zebrafish yme1l1b (79% identical), zebrafish yme1l1a (73% identical), Drosophila melanogaster YME1L (46% identical), Caenorhabditis elegans ymel-1 (40% identical). Paralogues in human: AFG3L2 (34% identical), SPG7 (29% identical).
Diseases named in the same sentence as YME1L1 in open-access papers:
YME1L1 is named in the same sentence as 52 diseases in open-access papers, as found by Europe PMC text mining. Sharing a sentence is not in itself a finding about the gene and the disease. The quoted sentences say what the papers report.
glioma (6 papers, 2022 to 2024). A benign or malignant brain and spinal cord tumor that arises from glial cells (astrocytes, oligodendrocytes, ependymal cells). "TIMM44 upregulation in glioma is possibly due to increased TIMM44 transcriptional machinery by the transcription factor GATA3 in a YME1L (YME1 Like 1 ATPase)-dependent manner." (PMID 36438483, 2022).
heart failure (6 papers, 2018 to 2024). Inability of the heart to pump blood at an adequate rate to meet tissue metabolic requirements. "In addition, mutations of YME1L1 gene in adult cardiomyocytes cause mitochondrial fragmentation, heart failure and premature death in mice." (PMID 33080837, 2020).
Ataxia (2 papers, 2019). Ataxia refers to impaired coordination of voluntary muscle movement. "Mitochondriopathies are also associated with many multisystemic diseases including infantile-onset developmental delay, muscle weakness, ataxia, and optic nerve atrophy caused by a homozygous mutation in the yeast mitochondrial escape 1-like 1 gene (YME1L1)." (PMID 31557225, 2019).
Atrophy (2 papers, 2020 to 2022). Any weakening or degeneration, especially through lack of use. "Patients carrying mutations in YME1L1 present with optic atrophy-11 (OPA11, MIM #617302), characterized by intellectual disabilities, muscular degradation and optic nerve atrophy, associated with abnormal OPA1 processing and mitochondrial fragmentation." (PMID 36475414, 2022).
breast carcinoma (2 papers, 2020 to 2024). "A higher frequency of mtDNA transfer in nuclear genome was observed in human breast cancer cell line MCF-7 by inactivating YME1L1 gene (a human homolog of yeast YME1)." (PMID 33080837, 2020). "Overexpression of YME1L1 in Basal breast cancer could contribute to the aggressive phenotype observed in this subtype by enhancing mitochondrial biogenesis and respiratory function." (PMID 39596229, 2024).
cardiomyopathy (2 papers, 2021 to 2022). A disease of the heart muscle or myocardium proper. "The 2 proteases CLPP and YME1L1 have a particular interest in our study, as their genetic inhibition induces cardiomyopathy." (PMID 35230976, 2022).
colorectal cancer (2 papers, 2017 to 2023). A primary or metastatic malignant neoplasm that affects the colon or rectum. "We conducted in silico YME1L1 mutation analysis in all colorectal cancer cases (n = 57) used for NUMT analysis in this study." (PMID 28356157, 2017). "Most of the mutations in Yme1L1 in human colorectal cancer fall into two categories: missense substitutions (~68%) and synonymous substitutions (20%)." (PMID 28356157, 2017).
chronic kidney disease (1 paper, 2025). Impairment of the renal function secondary to chronic kidney damage persisting for three or more months. "Dramatically, restoration of YME1L1 expression significantly alleviates cisplatin‐induced AKI and subsequent chronic kidney disease (CKD) through attenuating mitochondrial dysfunction via maintaining optic atrophy 1 (OPA1)‐mediated mitochondrial energy metabolism homeostasis." (PMID 39680752, 2025).
colorectal tumors (1 paper, 2017). "We identified that 16% of analyzed colorectal tumors contained mutations in the YME1L1 gene." (PMID 28356157, 2017). "We identified YME1L1, a human homolog of yeast YME1 (yeast mitochondrial DNA escape 1) to be frequently mutated in colorectal tumors." (PMID 28356157, 2017).
ischemia (1 paper, 2022). A hypoperfusion of the BLOOD through an organ or tissue caused by a PATHOLOGIC CONSTRICTION or obstruction of its BLOOD VESSELS, or an absence of BLOOD CIRCULATION. "The levels of OPA1, OMA1, and YME1L1 in the brain tissue surrounding the ischemia were detected by western blot and immunofluorescence staining in the adjacent section of TTC staining." (PMID 35395832, 2022).
Nephropathy (1 paper, 2025). A nonspecific term referring to disease or damage of the kidneys. "Moreover, the expression levels of SREBP1 and YME1L1 were closely correlated with the severity of kidney damage in AKI patients." (PMID 39680752, 2025).
neuroblastoma (1 paper, 2020). Neuroblastoma (NB) is the most common solid, extracranial childhood tumor. "As discussed by the authors, KIF1Bβ, which is frequently deleted in neuroblastoma, physiologically interacts with YME1L1, a mitochondrial protease, favoring OPA1 cleavage and mitochondrial fission." (PMID 33233365, 2020). "Overexpression of YME1L1 favored mitochondrial fragmentation, and ameliorated the prognosis of neuroblastoma, inducing the apoptosis of in vitro neuroblastoma cell lines." (PMID 33233365, 2020).
Sepsis (1 paper, 2025). Sepsis is defined as life-threatening organ dysfunction caused by a dysregulated host response to infection. "This study has found that YME1L1 showed significantly lower expression levels in sepsis samples." (PMID 40421007, 2025). "The low expression of YME1L1 may lead to mitochondrial dysfunctionality in patients with sepsis." (PMID 40421007, 2025). "Among them, YME1L1, THEM4, and COQ10A showed significantly lower expression levels in sepsis samples, while ECHDC3 exhibited markedly higher expression." (PMID 40421007, 2025). "Four biomarkers (YME1L1, ECHDC3, THEM4, and COQ10A) related to mitochondrial and macrophage polarization in sepsis were obtained by differential expression, machine learning, and expression validation." (PMID 40421007, 2025). "We think that both YME1L1 and ECHDC3 may be the potential role in the mechanism of sepsis which may provide new insights into the pathophysiology of the disease." (PMID 40421007, 2025). "Notably, RT-qPCR analysis confirmed that YME1L1, THEM4, and COQ10A exhibited significantly lower expression levels in sepsis samples." (PMID 40421007, 2025). "Therefore, machine learning and gene expression analysis were utilized in this study to identify YME1L1, ECHDC3, THEM4, and COQ10A as biomarkers for sepsis in our study." (PMID 40421007, 2025). "Subsequent gene expression analysis revealed that YME1L1, THEM4, and COQ10A exhibited significantly lower expression levels in sepsis patient samples from both the GSE95233 and GSE28750 datasets, while ECHDC3 demonstrated markedly higher expression in sepsis patients (p < 0.05)." (PMID 40421007, 2025). "Consequently, YME1L1, THEM4, COQ10A, and ECHDC3 were identified as biomarkers for sepsis." (PMID 40421007, 2025). "RT-qPCR results showed YME1L1, THEM4, and COQ10A were obviously lower expression in sepsis samples (p < 0.05), while ECHDC3 did not significant differences between sepsis and control samples." (PMID 40421007, 2025).
cancer (11 papers, 2012 to 2024). A tumor composed of atypical neoplastic, often pleomorphic cells that invade other tissues. "We also analyzed Yme1L1 mutations in other human cancer types and observed a high mutation frequency in all the tested cancer types." (PMID 28356157, 2017). "Therefore, mutations of YME1L1 gene may also be related to certain metabolic features of cancer cells." (PMID 33080837, 2020). "Given that disruptions in YME1L1 have been linked to impaired mitochondrial structure and increased production of reactive oxygen species (ROS), its upregulation in Basal tumors may support the high metabolic demands and proliferative capacity of these cancer cells." (PMID 39596229, 2024). "Since the Antp-TPR peptide did not increase the promoter activity of YME1L1 and GCP60 after induction of the mtUPR and Golgi stress, it is suggested that Antp-TPR might affect the erUPR specifically in cancer cells." (PMID 22913813, 2012).
tumor (8 papers, 2015 to 2025). "The high recurrence of genes like C1QBP and RPS3A in Luminal A, USP31 and RRM1 in Luminal B, and PSMD8 and YME1L1 in Basal subtypes highlights the subtype-specific regulatory networks that underlie tumor progression." (PMID 39596229, 2024). "Another study indicates that tumor suppressor KIF1B β regulates the structural and functional dynamics of mitochondria with YME1L1 and plays an important role in apoptosis mediated by mitochondria." (PMID 40421007, 2025). "While SIRT3 deacetylates mitochondrial metalloprotease YME1L1 to promote mitochondrial fusion and OXPHOS, thereby facilitating T cell infiltration into tumor tissue and enhancing anti-tumor immunity." (PMID 38773972, 2024).
YME1L1 also shares sentences with these, for which no sentence is quoted: infection (13 papers); optic atrophy (5); dilated cardiomyopathy (4); diabetes (2); intellectual disabilities (2); Lyme disease (2); microphthalmia (2); myocardial infarction (2); Obesity (2); osteosarcoma (2); pancreatic ductal adenocarcinoma (2); sarcoma (2); acute kidney injury (1); acute lymphoblastic leukemia (1); acute myeloid leukemia (1); autoimmune myocarditis (1); cataract (1); chronic myelogenous leukemia (1); co-infection (1); dental caries (1); hepatocellular carcinoma (1); inflammation (1); leukemia (1); lipid metabolic disorders (1); lupus nephritis (1); malaria (1); mitochondrial disease (1); Mitochondrial Dysfunction (1); motor developmental delay (1); nasopharyngeal carcinoma (1).
A further 7 diseases each share a sentence with YME1L1 in 1 paper.